SLC28A3 (solute carrier family 28 member 3)
Description:
Sodium-dependent, pyrimidine- and purine-selective. Involved in the homeostasis of endogenous nucleosides. Exhibits the transport characteristics of the nucleoside transport system cib or N3 subtype (N3/cib) (with marked transport of both thymidine and inosine). Employs a 2:1 sodium/nucleoside ratio. Transports uridine. Also able to transport gemcitabine, 3'-azido-3'-deoxythymidine (AZT), ribavirin and 3-deazauridine.
Synonyms: CNT3
Tractability: Antibody: UniProt places it where antibodies can reach, with high confidence; its Gene Ontology location is reachable by antibodies, with high confidence; UniProt predicts a signal peptide or a membrane-spanning region. PROTAC: a small molecule that binds it is known.
Target class: Transporter; SLC28 Na+-coupled nucleoside transport family; Electrochemical transporter; SLC28 and SLC29 families of nucleoside transporters; SLC superfamily of solute carriers
Safety:
Unwanted effects reported when the protein is acted on. In parentheses: how it was acted on, where the effect was seen, and who reports it.
cardiotoxicity (source: ClinPGx)
Gene: Protein-coding gene on chromosome 9 (84,275,457 to 84,340,758, reverse strand). Ensembl gene ENSG00000197506.
Subcellular location: Cell membrane (Isoform 1); Endoplasmic reticulum membrane (Isoform 2)
Pathways (Reactome):
Drug ADME: Azathioprine ADME; Ribavirin ADME
Transport of small molecules: Transport of nucleosides and free purine and pyrimidine bases across the plasma membrane
Gene Ontology:
Molecular function: protein binding; uridine transmembrane transporter activity; nucleoside:sodium symporter activity; purine nucleobase transmembrane transporter activity; purine-specific nucleoside:sodium symporter activity; pyrimidine- and adenosine-specific:sodium symporter activity; nucleoside transmembrane transporter activity
Biological process: nucleoside transmembrane transport; pyrimidine-containing compound transmembrane transport; uridine transmembrane transport; purine nucleobase transmembrane transport; purine nucleoside transmembrane transport; pyrimidine nucleoside transport; xenobiotic metabolic process; xenobiotic transmembrane transport; pyrimidine nucleobase transport; sodium ion transmembrane transport
Cellular component: endoplasmic reticulum membrane; plasma membrane; brush border membrane; membrane
Genetic constraint (gnomAD): Loss-of-function variants: 63 observed, 83.74 expected, observed/expected ratio (o/e) 0.75, 90% interval 0.61 to 0.93. The upper end of that interval is the gene's LOEUF score, 0.93, which puts it in group 3 of 6, group 1 being the genes least tolerant of losing a copy. Missense variants: 693 observed, 860 expected, observed/expected ratio (o/e) 0.81, 90% interval 0.76 to 0.86. Synonymous variants: 263 observed, 311.77 expected, observed/expected ratio (o/e) 0.84, 90% interval 0.76 to 0.93.
Homologues: Orthologues: chimpanzee SLC28A3 (99% identical), macaque SLC28A3 (96% identical), rabbit SLC28A3 (85% identical), dog SLC28A3 (82% identical), guinea pig SLC28A3 (81% identical), pig SLC28A3 (79% identical), mouse Slc28a3 (78% identical), rat Slc28a3 (78% identical), tropical clawed frog slc28a3 (62% identical), Drosophila melanogaster CNT2 (30% identical), Drosophila melanogaster CNT1 (29% identical), Caenorhabditis elegans slc-28.2 (25% identical), and 1 more. Paralogues in human: SLC28A1 (42% identical), SLC28A2 (41% identical).
Diseases named in the same sentence as SLC28A3 in open-access papers:
SLC28A3 is named in the same sentence as 25 diseases in open-access papers, as found by Europe PMC text mining. Sharing a sentence is not in itself a finding about the gene and the disease. The quoted sentences say what the papers report.
pancreatic cancer (8 papers, 2013 to 2022). "Variation rs7867504 in SLC28A3 was shown to be involved in gemcitabine pharmacobiology and toxicity in metastatic breast cancer patients receiving maintenance therapy or in patients with pancreatic carcinoma." (PMID 30545124, 2018).
cardiomyopathy (3 papers, 2019 to 2025). A disease of the heart muscle or myocardium proper. "Carrying the A allele in the SLC28A3- rs7853758 variant was associated with a lower risk of cardiomyopathy (OR = 0.36, 95% CI: 0.22–0.60), and the variant UGT1A6-rs17863783 was significantly associated with a 6.2-fold (95% CI: 2.5–15.4; p = 1.1 × 10−4) increased risk of severe cardiomyopathy." (PMID 40413218, 2025). "Moreover, carrying the A allele in the SLC28A3-rs7853758 variant was associated with a decreased risk effect on cardiomyopathy (OR = 0.31, 95% CI: 0.16–0.60)." (PMID 40413218, 2025). "The rs7853758 variant in the SLC28A3 gene has been identified as protective against cardiomyopathy." (PMID 40413218, 2025). "The CYP3A5-rs4646450-TT and the SLC28A3- rs7853758-AA genotypes were associated respectively with a 6.6-fold (95% CI: 1.7–25.7, p = 7.00 × 10−3) and 9.8-fold (95% CI: 1.7–56.0, p = 0.01) increased risk of cardiomyopathy." (PMID 40413218, 2025). "As a result, 20 studies were included (15 case-control and five cohorts), revealing several genes and variants associated with cardiomyopathy, among which, SLC28A3-rs7853758, RARG-rs2229774, P2RX7-rs208294 and P2RX7-rs3751143 variants gave the most consistent findings." (PMID 40413218, 2025). "Different variants in the Solute carrier (SLC) transporters: SLC28A3, SLC22A17, SLC22A7, and SLC22A6 were identified as associated with cardiomyopathy in CCS." (PMID 40413218, 2025). "A candidate gene study on early breast cancer patients that focused on the SLC28A3 gene found no cardiomyopathy association after anthracycline treatment, suggesting a potential specificity of this gene to CCS." (PMID 40413218, 2025). "Most research was done on doxorubicin-induced cardiomyopathy and for seven genetic variants in CELF4, GPR35, HAS3, RARG, SLC22A17, SLC22A7 and SLC28A3, replication studies were performed without consistent results." (PMID 36536332, 2022).
breast carcinoma (2 papers, 2022 to 2025). "In four pediatric cancer cohorts, the variant alleles of SLC28A3 rs7853758 and rs885004 were correlated with cardiotoxicity associated with anthracyclines (doxorubicin and daunorubicin), whereas this finding with SLC28A3 rs7853758 was not reproduced in cohorts of breast cancer or B-cell lymphoma." (PMID 35456712, 2022).
childhood cancer (2 papers, 2022 to 2025). "Pharmacogenomic testing is recommended for childhood cancer patients with indication for the anthracyclines daunorubicin and doxorubicin for specific variants of RARG, SLC28A3 and UGT1A6*4." (PMID 35872888, 2022). "Indeed, it would be interesting to add a genetic screening to the clinical guidelines for patients diagnosed with childhood cancer targeting the RARG- rs2229774 risk variant, the SLC28A3-rs7853758 protective variant or the harmful union of the P2RX7-rs208294 and P2RX7-rs3751143 variants." (PMID 40413218, 2025).
leukemia (2 papers, 2016 to 2023). A malignant (clonal) hematologic disorder, involving hematopoietic stem cells and characterized by the presence of primitive or atypical myeloid or lymphoid cells in the bone marrow and the blood. "In line with the present findings, SLC28A1, SLC28A2, and SLC28A3 were poorly expressed in primary bone marrow blasts and leukemia cell lines." (PMID 36834962, 2023). "The mRNA amounts of the main nucleoside transporters (NT) and intracellular metabolizing enzymes (ME), hENT1, hENT2 (SLC29A2), hCNT1 (SLC28A1), hCNT2 (SLC28A2), hCNT3 (SLC28A3), DCK and cN-II (NT5C2), were measured in 50 pediatric leukemia cases by RQ-PCR." (PMID 27391351, 2016).
COVID-19 (1 paper, 2023). A disease caused by infection with severe acute respiratory syndrome coronavirus 2. "Genes such as SLC28A3 play roles in many biological processes spanning nutrient metabolism to COVID-19 therapy pharmacogenomics, and we cannot assume a phenotypic outcome from gain or LOF variants." (PMID 37582787, 2023).
hearing loss (1 paper, 2015). "Finally, it should be noted that SLC28A3 is directly involved in the metabolism of two drugs (anthracycline and gemcitabine) and in the corresponding side effects/adverse reactions, which also include hearing loss." (PMID 26188009, 2015).
lung carcinoma (1 paper, 2020). "Also, the expression levels of nucleoside transporter SLC28A3 were not changed in lung cancer tissues." (PMID 32638267, 2020).
neuromyelitis optica (1 paper, 2018). A rare inflammatory disease of the central nervous system characterized mainly by attacks of uni- or bilateral optic neuritis (ON) and acute myelitis. "The rs10868138 in SLC28A3 is a less studied variant; however, it was recently connected with higher concentration of azathioprine in erythrocytes of patients with neuromyelitis optica, suggesting that it may be functional in vivo." (PMID 30545124, 2018).
neutropenia (1 paper, 2022). A decrease in the number of neutrophils found in the blood. "Evidence from studies in ALL children indicates significant associations between SLC29A1, SLC28A2, SLC28A3 and ABCC4 variants and one or more of the hematological toxicity manifestations (neutropenia, agranulocytosis and leukopenia)." (PMID 36015138, 2022). "ABCC4, SLC19A1, SLC28A3, SLC29A1, SLCO1B1 genetic variants were associated with thiopurine-related toxicities; neutropenia, hepatotoxicity and treatment interruption, especially in Asians." (PMID 36015138, 2022).
Obesity (1 paper, 2019). Accumulation of substantial excess body fat. "Studies have shown that SLC28A3 is associated with obesity, and it may be associated with the lipid-lowering response of statins." (PMID 30968251, 2019).
cancer (11 papers, 2013 to 2025). A tumor composed of atypical neoplastic, often pleomorphic cells that invade other tissues. "Pharmacogenetic test for SLC28A3 rs7853758 is suggested before treatment with anthracyclines in pediatric cancer patients." (PMID 36312261, 2022). "Variants in ABC transporter genes, including ABCB1, ABCC4, and ABCC3, as well as solute carrier (SLC) genes such as SLC28A3, are known to influence the pharmacokinetics of numerous anti-cancer agents, including fluoropyrimidines, methotrexate, anthracyclines, and irinotecan." (PMID 40428413, 2025). "SLC28A3 plays a role in the influx of anthracyclines into cancer cells." (PMID 36312261, 2022).
tumor (5 papers, 2015 to 2025). "For NSCLC, recommendations comprised larotrectinib/entrectinib (unconventional SLC28A3::NTRK2 gene fusion), capmatinib (MET amplification, GCN: 16.7), afatinib (RBPMS::NRG1 gene fusion), and dabrafinib/trametinib in the case of a BRAF p.Val600Glu, and a non-V600E BRAF mutated tumor, respectively." (PMID 38136436, 2023). "We also noted a few transporters which were moving in the opposite direction in the human dataset compared to the rat reflux model, including SLC28A3 and SCLO4A1, which show strong heterogeneity in the EAC tumor samples, potentially contributing to the opposing trend." (PMID 38139823, 2023).
SLC28A3 also shares sentences with these, for which no sentence is quoted: metastatic prostate carcinoma (2 papers); prostate carcinoma (2); B-cell lymphoma (1); bladder cancer (1); Bladder Urothelial Carcinoma (1); chronic lymphocytic leukaemia (1); leukopenia (1); microcephaly (1); neuroblastoma (1); osteosarcoma (1); Tremor (1); viral infections (1).